IRAK1 (interleukin 1 receptor associated kinase 1)
Diseases named in the same sentence as IRAK1 in open-access papers (continued):
Sharing a sentence is not in itself a finding about the gene and the disease.
atherosclerosis (15 papers, 2015 to 2024). A disease characterized by the build-up of fatty material and calcium deposition in the arterial wall resulting in partial or complete occlusion of the arterial lumen. "miR-146a has been reported to be involved in the inflammatory process of atherosclerosis, by targeting interleukin-1 receptor-associated kinase 1 (IRAK-1) and TNF receptor-associated factor 6 (TRAF-6)." (PMID 31092195, 2019). "This binds to target mRNAs including tumor necrosis factor-α (TNF-α), C-reactive protein and interleukin-1 receptor-associated kinase-1 (IRAK1), which affect vascular damage responses and inflammation-related atherosclerosis in the development of stroke." (PMID 27164084, 2016). "ECs, a major cell type involved in plaque formation in atherosclerosis, is also found to be regulated by IRAK1." (PMID 35345264, 2022). "It is known that in atherosclerosis there is an activation of the inflammatory cascade mediated by the TLR pathway through IRAK1/Nf-kβ." (PMID 35495944, 2022). "Much of the collected data has indicated that IRAK1 is highly associated with the pathogenesis of CVD, especially in the development of atherosclerosis, MI, and HF." (PMID 35345264, 2022). "IRAK1 also stimulates VSMC proliferation, which is a pivotal pathogenic process in the development of atherosclerosis." (PMID 35345264, 2022). "Atherosclerosis involves activation of the IRAK1/TRAF6/NF-κB inflammatory cascade, which is negatively regulated by miR146a." (PMID 29902229, 2018). "We therefore provided further insight into VSMC-derived foam cell formation and offered IRAK1 as a promising target for the prevention and treatment of atherosclerosis." (PMID 26512959, 2015). "Activation of IRAK1 enhances production of IL-10 and patients with atherosclerosis often have an elevated level of IL-10, implying that the IRAK1-mediated innate immune response may play an important role in the development of atherosclerosis." (PMID 35345264, 2022). "Correlations among constitutive expression of IRAK1 in the peripheral blood mononuclear cells isolated from patients with atherosclerosis, elevated levels of the plasma IL-10, and the stimulation effect of IRAK1 on IL-1, imply direct involvement of IRAK1 in atherosclerotic development." (PMID 35345264, 2022). "IRAK1 is a threonine/serine kinase that is related to the pathogenesis of atherosclerosis." (PMID 35706446, 2022). "A role for IRAK1 as a driver for the inflammatory component in atherosclerosis has been proposed." (PMID 30279971, 2018). "Finally, aortic atherosclerosis burden and recruitment of leukocytes into the vessel wall were undistinguishable between the two groups, despite higher levels of Irak1 and Traf6 mRNA and protein in the aorta of fat-fed mice lacking hematopoietic miR-146a expression." (PMID 29902229, 2018). "Thus, an ample mechanistic rationale exists for the study of IRAK1 inhibition in atherosclerosis." (PMID 30279971, 2018). "A role for miR-146a in atherosclerosis is suggested by its ability to negatively regulate several pro-inflammatory factors that promote disease progression, including Toll-like receptor 4 (TLR4), IL-1 receptor-associated kinase 1 (IRAK1), and TNF receptor-associated protein factor 6 (TRAF6)." (PMID 29902229, 2018). "In addition, miR-146a-5p targets TRAF6 and IRAK1, proteins that are part of the CD40 signaling pathway; CD40, which serves an important role in cellular communication during inflammatory responses, is implicated in atherosclerosis." (PMID 26956024, 2016). "Several risk markers related to the immune response that have key roles in atherosclerosis were identified, including the top aging marker MMP8, disease markers KIR3DL1 and MAGEA6, network markers based on degree (RBM10, PJA2, and CMTM6), and network markers based on betweenness (IRAK1 and VAMP8)." (PMID 35706446, 2022).
atherosclerosis (continued). "Therefore, the down-regulation of miR-146a may increase inflammation-related atherosclerosis and affect vascular damage response by increasing the levels of TNF-α, TRAF6, and IRAK1." (PMID 27164084, 2016). "Although IRAK1 inhibition has not been tested directly in clinical CVD, the positive results recently reported for IL-1β blockade in atherosclerosis lend support to the testing of this hypothesis." (PMID 30279971, 2018).
Autoimmunity (13 papers, 2010 to 2025). The occurrence of an immune reaction against the organism's own cells or tissues. "Polymorphism studies revealed some allelic variants of IRAK-1 are associated with the higher risk of autoimmunity." (PMID 33297945, 2020). "The IRAK1 gene is located within the Xq28 locus that contains several polymorphisms associated with increased susceptibility to autoimmunity, including systemic lupus erythematous, systemic sclerosis, and RA." (PMID 28271077, 2017). "The impact of MyD88 and IRAK1 deficiency on autoimmunity has been quite well documented." (PMID 20981241, 2010). "As a conclusion, IRAK-1 contribute to autoimmunity through promoting differentiation and activation of various T cells subsets." (PMID 33297945, 2020). "The relationship between IRAK1 and autoimmunity has been explored." (PMID 35669566, 2022). "There is mounting evidence documenting that the crippling of this pathway at the level of TLR, MyD88, or IRAK1/4 may confer therapeutic efficacy in autoimmunity and auto-inflammatory diseases." (PMID 20981241, 2010). "Suppression of IRAK1 catalytic activity has been shown to prevent LN in mice, whereas PTPN6 ablation promotes Th1 cell differentiation and induces autoimmunity." (PMID 38912505, 2024). "In contrast, crossing ABIN1[D485N] mice to knock-in mice expressing catalytically inactive mutants of IRAK1 or IRAK4 prevented splenomegaly, autoimmunity, and liver and kidney inflammation." (PMID 27807192, 2016). "Our earlier studies had shown that autoimmunity and glomerulonephritis in ABIN1[D485N] mice were prevented by crossing to MyD88 KO mice or mice expressing kinase-inactive mutants of IRAK4 or IRAK1." (PMID 31694920, 2019). "Crossing these mice with mice expressing catalytically inactive IRAK1 or IRAK4 mutants prevented the development of splenomegaly, autoimmunity, and liver and kidney inflammation, supporting the role of these enzymes as targets in human autoinflammatory diseases." (PMID 30279971, 2018).
diffuse large B-cell lymphoma (13 papers, 2014 to 2025). "An IRAK1/4 inhibitor was also effective in MYD88 L265P mutated diffuse large B cell lymphoma (DLBCL)." (PMID 26068967, 2015). "Targeting the IRAK1/4 signaling pathway has emerged as a promising therapeutic strategy for various malignancies, including diffuse large B-cell lymphoma (DLBCL), myelodysplastic syndrome, breast cancer, head and neck cancer, and pancreatic cancer." (PMID 40083694, 2025). "IRAK1 is overexpressed in B-cell lymphomas such as Waldenström’s macroglobulinemia (WM) and ABC subtype diffused large B-cell lymphoma (DLBCL) cells." (PMID 38792088, 2024).
melanoma (12 papers, 2014 to 2025). A malignant, usually aggressive tumor composed of atypical, neoplastic melanocytes. "About 42% of melanoma cell lines constitutively express phospho-IRAK1, which has been implicated in the aggressiveness of the disease." (PMID 37370720, 2023). "IRAK1 gene expression elevated in highly metastatic versus normal variants of melanoma cells grafted into immunosuppressed newborn rats." (PMID 30279971, 2018). "In another study, IRAK1 gene transcript levels were found to be elevated in highly metastatic versus normal variants of human melanoma cells grafted into immunosuppressed newborn rats, suggesting a role for IRAK1 in melanoma metastasis." (PMID 30279971, 2018). "In another study, the use of the IRAK1/4 inhibitor (EMD Millipore CAS 509093-47-4) enhanced vinblastine activity against melanoma." (PMID 38796478, 2024). "Phospho-IRAK1 is constitutively expressed in 42% of melanoma cell lines, and IRAK1/4 inhibition in combination with certain chemotherapeutic agents enhanced cell killing." (PMID 30279971, 2018). "Chemical inhibition of IRAK1 in melanoma cells resulted in increased apoptosis in vitro and in vivo." (PMID 27619757, 2016). "A combined treatment of vinblastine and small interfering RNAs (siRNAs) inhibited IRAK4 and IRAK1, showing reduced tumor growth and increased survival rate of melanoma xenograft model of mice." (PMID 27845762, 2016). "In the melanoma cell lines, both IRAK4 and IRAK1 are highly expressed and activated, and promote primary melanoma progression." (PMID 27619757, 2016). "Chemical inhibition of IRAK1 was also carried out with the IRAK-1/4 inhibitor which has been shown to increase apoptosis in melanoma cells in vitro and in vivo and to inhibit signaling and cell viability in MDS." (PMID 26527316, 2015). "As previously discussed (in the Section IRAK-1) some melanomas constitutively express active, phosphorylated forms of IRAK-1 and IRAK-4." (PMID 25452754, 2014). "IRAK1/4 inhibitor, in combination with vinblastine, improved tumor growth inhibition in a xenograft mouse model and was also found to enhance the apoptosis of melanoma cell lines." (PMID 37370720, 2023). "Similarly, in a xenograft mouse model of melanoma, IRAK1/4 inhibitor I in combination with vinblastine improved TGI and survival relative to either agent alone." (PMID 30279971, 2018). "Constitutive phosphorylated states of IRAK4 and IRAK1 have been reported in melanoma patients." (PMID 27845762, 2016). "The use of rapid subtraction hybridization analysis was used to identify IRAK-1 as one of eight genes that are differentially expressed in metastatic cells compared to parental human melanoma cell lines, with IRAK-1 expression being upregulated in the metastatic variants." (PMID 25452754, 2014). "IRAK-1 may be particularly relevant to the pathogenesis of melanoma." (PMID 25452754, 2014). "In both melanoma and T cell acute lymphoblastic leukemia (T-ALL), a small-molecule IRAK1/4 inhibitor suppressed cell proliferation and enhanced chemotherapeutic responses." (PMID 34906138, 2021). "The high expression (mRNA and protein) of IRAK1 as well as activated IRAK1 (T209) observed in myelodysplastic syndrome, acute myeloid leukaemia, melanoma and HCC showed the probable correlation between IRAK1 and its phosphorylated activation." (PMID 27619757, 2016). "Inhibiting IRAK-4 rather than IRAK-1 using shRNA was more effective at sensitizing melanoma tumors and T-ALL cells to chemotherapies." (PMID 25452754, 2014). "Inhibition of IRAK-1 and IRAK-4, using pharmacological inhibitor or siRNA, sensitized melanoma tumors expressing phosphorylated forms of these IRAKs to cytotoxic chemotherapies in vivo, raising the possibility that IRAK family proteins may be potential therapeutic targets in cancer." (PMID 25452754, 2014). "Our group has also found IRAK-1 and/or IRAK-4 to localize to the nucleus of melanoma cells, but not melanocytes (Geng, unpublished data)." (PMID 25452754, 2014).
acute myeloid leukemia (11 papers, 2014 to 2024). Acute myeloid leukemia (AML) is a group of neoplasms arising from precursor cells committed to the myeloid cell-line differentiation. "Pacritinib, an IRAK1 inhibitor, which has been shown to be effective in myelofibrosis, and acute myeloid leukemia." (PMID 35669566, 2022). "Recently, investigators were able to demonstrate the potential of IRAK1-targeted small-molecule inhibition in acute myeloid leukemia (AML) as well." (PMID 33530653, 2021). "The inhibition of IRAK1 is also effective at reducing the growth of acute myeloid leukemia (AML) cell lines and primary AML patient cells." (PMID 35022428, 2022). "The pharmaceutical IRAK1/4 inhibitor has already been frequently used for acute myeloid leukemia (AML) treatments." (PMID 27619757, 2016). "They reported that the mRNA levels of IRAK1 are upregulated in nearly all cancer types, with the notable exceptions of THCA and acute myeloid leukemia (LAML), where its expression is much lower compared to normal tissues." (PMID 39451208, 2024). "In acute myeloid leukemia (AML), over-expressed IRAK1 and universal activation were frequent." (PMID 27619757, 2016). "IRAK1 was recently implicated as a novel therapeutic target in myelodysplastic syndrome (MDS) and acute myeloid leukemia (AML), but its function in most solid tumors remains unknown." (PMID 26527316, 2015). "In acute myeloid leukemia (AML) and CML, blocking IL-1 signaling (for example, with anti-IL-1RA or anti-IL1RAP antibodies, IRAK1/4 inhibitors, IL-11/4 inhibitors, AP antibodies) eliminates LSCs in the TME, thereby preventing recurrence in patients." (PMID 36761742, 2023). "IRAK1 transcriptional expression has negative prognostic impact in Myelodysplasic syndromes (MDS) and acute myeloid leukemias (AML)." (PMID 26068967, 2015).
colitis (11 papers, 2010 to 2022). Inflammation of the colon. "Next, investigations proved that inhibition of IRAK1/4 activity demonstrated a protective effect on DSS-induced colitis in mice." (PMID 35699749, 2022). "Our study suggests that the IRAK1/4 inhibitor can reduce intestinal injury and the inflammatory response in colitis." (PMID 35699749, 2022). "Based on these facts, this study investigated the effect of IRAK1/4 inhibitors on IRAK1/4 activity suppression in an experimental colitis model, providing a reference for UC treatment." (PMID 35699749, 2022). "In vivo, inhibition of IRAK1, in mice with colitis-induced tumorigenesis, reduced the inflammatory response and inhibited the epithelial–mesenchymal transition." (PMID 34576039, 2021). "Although, ginsenoside Rb1 and its metabolites have been confirmed playing an beneficial role in inflammatory responses in TNBS-induced colitis by inhibiting IRAK-1 activation, which contributes to activate IKKβ, linking with NF-κB and MAPK pathways." (PMID 24504372, 2014). "Our experiment showed that a certain concentration of IRAK1/4 inhibitor could effectively relieve DSS-induced colitis in mice." (PMID 35699749, 2022). "Therefore, we established that the IRAK1/4 inhibitor effectively improves colitis induced by DSS, partly by inhibiting the TLR4/NF-κB pathway, reducing inflammation, and maintaining the integrity of the colonic barrier." (PMID 35699749, 2022). "For instance, EVs containing miR‐146a could target TRAF6 and IRAK1 to ameliorate experimental colitis." (PMID 35582765, 2022). "In our study, mice were successfully induced with colitis by freely administering a 3% DSS solution for 7 consecutive days through drinking and then pharmacologically inhibiting IRAK1/4 activity using the IRAK1/4 inhibitor." (PMID 35699749, 2022). "It has been exhibited the therapeutic intervention such as vesicles containing miR-146a, attenuate the experimental colitis in the animals by inhibition of TRAF-6 and IRAK-1." (PMID 33297945, 2020). "When IRAK1 is suppressed by small molecule treatment, it has been shown to block the TLR4-mediated inflammatory response, as well as DSS- or LPS-induced colitis and septic shock." (PMID 28680194, 2017). "Therefore, in this study, after inducing experimental colitis in mice with 3% dextran sulfate sodium (DSS), different concentrations of IRAK1/4 inhibitors were administered intraperitoneally." (PMID 35699749, 2022). "Rb1 and compound K appear to block IRAK-1 and NFκB activation and thereby reduce pro-inflammatory cytokines, IL-1β, TNF-α and IL-6 and cytokine effectors iNOS and Cox-2 in 2,4,6-trinitrobenzene sulfonic acid (TNBS)-treated mice, another model of colitis." (PMID 22070864, 2011). "This is in agreement with other studies that found that male mice respond faster and develop a more significant and aggressive colitis relative to female mice when exposed to DSS, and that STAT-1 deficiency or IRAK-1 deficiency render male, but not female, mice more resistant to DSS-induced colitis." (PMID 30619283, 2018).
myelodysplastic syndrome (11 papers, 2015 to 2023). A clonal hematopoietic disorder characterized by dysplasia and ineffective hematopoiesis in one or more of the hematopoietic cell lines. "This strategy has demonstrated preclinical efficacy in tumours harbouring MYD88 mutations, and preclinical studies of IRAK1/4 small-molecule inhibitors have reported encouraging preliminary results in melanoma, myelodysplastic syndrome (MDS) and T-cell acute lymphoblastic leukaemia (T-ALL)." (PMID 28829404, 2017). "IRAK1 inhibition has been proposed as a therapeutic strategy for myelodysplastic syndromes (MDS), as well as MPNs, based on preclinical studies." (PMID 34140953, 2021). "It was reported that the blockade of IRAK1/4 is effective at eradicating myelodysplastic syndrome (MDS) cells by inhibiting growth and inducing apoptosis through the deactivation of NF-κB35." (PMID 35022428, 2022). "Constitutive signaling of IRAK1 has, for example, been observed in T cell acute lymphoblastic leukemia (T-ALL) and myelodysplastic syndrome (MDS)." (PMID 33530653, 2021). "Furthermore, IRAK1 was overexpressed in 20–30% of patients with myelodysplastic syndromes (MDS)." (PMID 37370720, 2023).
COVID-19 (9 papers, 2020 to 2024). A disease caused by infection with severe acute respiratory syndrome coronavirus 2. "Proteins that were decreased in abundance in fatal COVID-19 included the epithelial damage-associated molecular pattern IL-33, IL-1 receptor-associated kinase-1 (IRAK1), and the lymphocyte receptors CD5 and CD6." (PMID 34710339, 2022). "Likewise, TLR4 and its downstream elements (including Myd88, IRAK1 and TRAF6, and NF-κB - dependent genes) were significantly upregulated in PBMCs from 20 human COVID-19 patients." (PMID 38439942, 2023).